SPAM1 (sperm adhesion molecule 1)
Description:
Involved in sperm-egg adhesion. Upon fertilization sperm must first penetrate a layer of cumulus cells that surrounds the egg before reaching the zona pellucida. The cumulus cells are embedded in a matrix containing hyaluronic acid which is formed prior to ovulation. This protein aids in penetrating the layer of cumulus cells by digesting hyaluronic acid.
Synonyms: PH20; HYAL5; PH-20; SPAG15; HEL-S-96n; HYA1
Tractability: Antibody: its Gene Ontology location is reachable by antibodies, with high confidence; UniProt places it where antibodies can reach, with medium confidence; UniProt predicts a signal peptide or a membrane-spanning region.
Gene: Protein-coding gene on chromosome 7 (123,925,237 to 123,971,414, forward strand). Ensembl gene ENSG00000106304.
Subcellular location: Cell membrane
Pathways (Reactome):
Metabolism: Hyaluronan degradation
Reproduction: Interaction With Cumulus Cells And The Zona Pellucida
Gene Ontology:
Molecular function: hyalurononglucosaminidase activity
Biological process: binding of sperm to zona pellucida; carbohydrate metabolic process; hyaluronan catabolic process; fusion of sperm to egg plasma membrane involved in single fertilization; single fertilization
Cellular component: acrosomal vesicle; plasma membrane
Genetic constraint (gnomAD): Loss-of-function variants: 17 observed, 25.25 expected, observed/expected ratio (o/e) 0.67, 90% interval 0.46 to 1.01. The upper end of that interval is the gene's LOEUF score, 1.01, which puts it in group 4 of 6, group 1 being the genes least tolerant of losing a copy. Missense variants: 501 observed, 585.99 expected, observed/expected ratio (o/e) 0.85, 90% interval 0.79 to 0.92. Synonymous variants: 180 observed, 199.45 expected, observed/expected ratio (o/e) 0.9, 90% interval 0.8 to 1.02.
Homologues: Orthologues: chimpanzee SPAM1 (97% identical), macaque SPAM1 (88% identical), rabbit SPAM1 (66% identical), pig SPAM1 (60% identical), mouse Hyal5 (59% identical), dog SPAM1 (59% identical), guinea pig SPAM1 (58% identical), rat Hyal5 (58% identical), mouse Spam1 (54% identical), rat Spam1 (51% identical), tropical clawed frog spam1 (44% identical), zebrafish spam1 (34% identical), and 1 more. Paralogues in human: HYAL4 (39% identical), HYAL1 (33% identical), HYAL2 (32% identical), HYAL3 (30% identical).
Diseases named in the same sentence as SPAM1 in open-access papers:
SPAM1 is named in the same sentence as 32 diseases in open-access papers, as found by Europe PMC text mining. Sharing a sentence is not in itself a finding about the gene and the disease. The quoted sentences say what the papers report.
Infertility (4 papers, 2005 to 2022). "It should be noted that in domestic animals CD-associated infertility has been shown to be due to poor passage through hyaluronate swim-up medium and failure to bind to the zona pellucida, both of which are functions of Spam1." (PMID 16092963, 2005). "This silencing would be adaptive since overexpression of Spam1 and Hyal5 leads to their mis-expression in CDs, which are abnormally retained and which lead to infertility." (PMID 16092963, 2005).
colon cancer (1 paper, 2023). "The activity of multiple hyaluronidase isoforms (HYAL1, 2, 3, and SPAM1) is increased in colon cancer patients, and the increased HYAL1 and HYAL2 are particularly closely related to the aggressiveness of cancer." (PMID 37568202, 2023).
diabetes (1 paper, 2014). "Ontological classification demonstrates that these 14 genes are associated with diabetes (ALMS1P; RAET1L; GYS1; RBM47; EFR3B), cancer (RPL27A; SPAM1; PTCH1; ZNF277; USP35; CDC86), or metabolism (C3orf15; AOC2; GOT1)." (PMID 24885560, 2014).
glioma (1 paper, 2023). A benign or malignant brain and spinal cord tumor that arises from glial cells (astrocytes, oligodendrocytes, ependymal cells). "In TCGA and GEPIA databases, we found that among the 6 human hyaluronidases (HYAL1, HYAL2, HYAL3, HYAL4, HYALP1, SPAM1), only HYAL2 expression was highest in glioma." (PMID 37568202, 2023). "In the present study, our results confirmed that among the six hyaluronidases (HYAL1, HYAL2, HYAL3, HYAL4, HYALP1, SPAM1), only HYAL2 was overexpressed in glioma patients, and HYAL2 overexpression was negatively correlated with the survival time of glioma patients." (PMID 37568202, 2023).
laryngeal carcinoma (1 paper, 2014). Carcinoma that arises from the laryngeal epithelium. "A number of reports demonstrate that also PH-20 or SPAM1, which is thought to be a testicular hyaluronidase, is a tumour marker for breast and laryngeal cancer." (PMID 25126569, 2014).
multiple sclerosis (1 paper, 2014). A progressive autoimmune disorder affecting the central nervous system resulting in demyelination. "We recently reported that a membrane-associated hyaluronidase, PH20 (SPAM1) is elevated in adult demyelinating multiple sclerosis lesions and digests high molecular weight forms of HA to a range of lower molecular weight HA fragments that block preOL maturation." (PMID 25390897, 2014).
osteoarthritis (1 paper, 2009). A noninflammatory degenerative joint disease occurring chiefly in older persons, characterized by degeneration of the articular cartilage, hypertrophy of bone at the margins and changes in the synovial membrane. "Expressions of β-D-hexosaminidase, β-D-glucuronidase, hyaluronidase, sperm adhesion molecule 1 and klotho genes were measured in synovial fibroblasts and synovial membrane samples of patients with rheumatoid arthritis and osteoarthritis by real-time PCR." (PMID 19442276, 2009).
sterility (1 paper, 2022). "Five genes (Tsga10, Terb1, Stra8, Tex14, and Spam1) were predicted to be associated with sterility in male and female Mule ducks." (PMID 36386800, 2022).
varicocele (1 paper, 2024). A condition characterized by the dilated tortuous veins of the spermatic cord with a marked left-sided predominance. "Additionally, proteins such as enkurin (ENKUR), semenogelin-1 and -2 (SEMG1/2), sperm adhesion molecule 1 (SPAM1), and CABYR serve as indicators of reduced semen quality in bilateral varicocele patients." (PMID 39685846, 2024).
tumor (42 papers, 2013 to 2026). "VCN-01 is an oncolytic adenovirus armed with a soluble version of human hyaluronidase (PH20; SPAM1) to degrade hyaluronic acid from the tumor matrix." (PMID 32340119, 2020). "For instance, TCVs containing the Spam1 gene express hyaluronidase, degrading the ECM, enhancing blood flow, reducing tumor hypoxia, and modulating the immune environment, thereby elevating antitumor efficiency and reducing tumor recurrence risk." (PMID 38693104, 2024). "Subsequently, we confirmed well-characterized oncogenes among tumor-related loci (such as EGFR and KIT) and detected novel genes that gained chromosome sequences (such as AASS, HYAL4, NDUFA5 and SPAM1) in both LGG and HGG." (PMID 23451178, 2013). "The pro-tumor effect of the HA-accumulating fibroblasts was highly dependent on HA, as enzymatic degradation of HA by either co-expression of the full-length human SPAM1 gene (PH20-FL) or by systemic administration of PEGPH20 significantly hindered tumor growth." (PMID 31762938, 2019).
cancer (10 papers, 2005 to 2025). A tumor composed of atypical neoplastic, often pleomorphic cells that invade other tissues. "PH20 (or Spam1) belongs to a neutral-active hyaluronidase and is detected primarily in testes and in a variety of cancers including HNSCC tumors." (PMID 28837080, 2017).
neurodegenerative disease (1 paper, 2024). A disorder of the central nervous system characterized by gradual and progressive loss of neural tissue and neurologic function. "In this study, we combined whole-transcriptome sequencing and proteomic analysis to further investigate the mechanism through which SPAM1 exerts neuroprotective effects, thereby laying the pharmacological foundation for the use of SPAM1 as a therapeutic agent for neurodegenerative diseases." (PMID 38612681, 2024).
SPAM1 also shares sentences with these, for which no sentence is quoted: breast carcinoma (4 papers); pancreatic cancer (3); infection (2); autism spectrum disorder (1); benign tumors (1); chondrosarcoma (1); Cognitive impairment (1); diffuse large B-cell lymphoma (1); endometrioid ovarian cancer (1); female sterility (1); gastric cancer (1); glioblastoma (1); head and neck squamous cell carcinoma (1); hepatocellular carcinoma (1); liver fibrosis (1); male infertility (1); metastatic cancer (1); ovarian carcinoma (1); prostate carcinoma (1); rheumatoid arthritis (1).